GNGT1 (G protein subunit gamma transducin 1)
Description:
Guanine nucleotide-binding proteins (G proteins) are involved as a modulator or transducer in various transmembrane signaling systems. The beta and gamma chains are required for the GTPase activity, for replacement of GDP by GTP, and for G protein-effector interaction.
Synonyms: GNG1; HG3G1
Tractability: Antibody: UniProt places it where antibodies can reach, with high confidence; its Gene Ontology location is reachable by antibodies, with medium confidence. PROTAC: ubiquitination databases record sites on it.
Gene: Protein-coding gene on chromosome 7 (93,591,329 to 93,911,265, forward strand). Ensembl gene ENSG00000127928.
Subcellular location: Cell membrane
Pathways (Reactome):
Signal Transduction: Ca2+ pathway; Extra-nuclear estrogen signaling; G alpha (12/13) signalling events; G alpha (i) signalling events; G alpha (q) signalling events; G alpha (s) signalling events; G alpha (z) signalling events; G beta:gamma signalling through BTK; G beta:gamma signalling through CDC42; G beta:gamma signalling through PI3Kgamma; G beta:gamma signalling through PLC beta; G-protein activation; GPER1 signaling; Glucagon-type ligand receptors
Hemostasis: ADP signalling through P2Y purinoceptor 1; ADP signalling through P2Y purinoceptor 12; Prostacyclin signalling through prostacyclin receptor; Thrombin signalling through proteinase activated receptors (PARs); Thromboxane signalling through TP receptor
Neuronal System: Activation of G protein gated Potassium channels; Inhibition of voltage gated Ca2+ channels via Gbeta/gamma subunits; Presynaptic function of Kainate receptors
Metabolism: Adrenaline,noradrenaline inhibits insulin secretion; Glucagon-like Peptide-1 (GLP1) regulates insulin secretion
Sensory Perception: Activation of the phototransduction cascade; Inactivation, recovery and regulation of the phototransduction cascade
Cellular responses to stimuli: High laminar flow shear stress activates signaling by PIEZO1 and PECAM1:CDH5:KDR in endothelial cells
Disease: ADORA2B mediated anti-inflammatory cytokines production
Metabolism of proteins: Cooperation of PDCL (PhLP1) and TRiC/CCT in G-protein beta folding
Transport of small molecules: Vasopressin regulates renal water homeostasis via Aquaporins
Gene Ontology:
Molecular function: protein binding; G-protein beta-subunit binding; GTPase activity
Biological process: G protein-coupled receptor signaling pathway; signal transduction
Cellular component: heterotrimeric G-protein complex; plasma membrane; photoreceptor disc membrane; photoreceptor inner segment; photoreceptor outer segment
Homologues: Orthologues: chimpanzee GNGT1 (100% identical), dog GNGT1 (100% identical), macaque GNGT1 (100% identical), guinea pig GNGT1 (99% identical), pig GNGT1 (99% identical), rabbit GNGT1 (99% identical), mouse Gngt1 (97% identical), rat Gngt1 (95% identical), tropical clawed frog gngt1 (84% identical), zebrafish gngt1 (66% identical), Drosophila melanogaster Ggamma1 (32% identical). Paralogues in human: GNG11 (76% identical), GNGT2 (59% identical), GNG12 (34% identical), GNG3 (34% identical), GNG4 (32% identical), GNG2 (31% identical), GNG7 (31% identical), GNG8 (30% identical), GNG10 (28% identical), GNG5 (24% identical), GNG5B (23% identical).
Diseases named in the same sentence as GNGT1 in open-access papers:
GNGT1 is named in the same sentence as 23 diseases in open-access papers, as found by Europe PMC text mining. Sharing a sentence is not in itself a finding about the gene and the disease. The quoted sentences say what the papers report.
gastric cancer (3 papers, 2024 to 2025). A primary or metastatic malignant neoplasm involving the stomach. "Tumor cell regions were demarcated using gastric cancer-specific marker genes (KRT17/PRAME/GNGT1/GJB5/PI3)." (PMID 40452847, 2025).
medulloblastoma (3 papers, 2021 to 2024). A malignant, invasive embryonal neoplasm arising from the cerebellum. "Some studies found that GNGT1 may be used as a biomarker of medulloblastoma, and its mutation may be related to neuroautoimmune diseases, such as multiple sclerosis, providing a new angle to evaluate the inherited causes of neurodegeneration." (PMID 39739972, 2024). "One study showed that GNGT1 could serve as a marker of medulloblastoma." (PMID 33505535, 2021).
breast carcinoma (2 papers, 2019 to 2021). "Network analysis on the cancer genome atlas (TCGA) breast cancer dataset revealed interaction between CXCL12 and CXCR7 (ACKR3), and a number of G-protein family members (GNG5, GNB4, GNB2, GNG12, GNG7, GNGT1, and GNAI3)." (PMID 30993013, 2019). "It is worth noting that the remaining genes, such as GNGT1 and UGT1A7, have not been documented to be associated with breast cancer." (PMID 35096840, 2021).
Stroke (2 papers, 2019 to 2023). Sudden impairment of blood flow to a part of the brain due to occlusion or rupture of an artery to the brain. "LRRK2, CALM1, CXCR4, TLR4, CTNNB1, and CXCR2 may be implicated in AF and the hub-genes of CD19, FGF9, SOX9, GNGT1, and NOG may be associated with stroke." (PMID 30760287, 2019).
autoimmune disease (1 paper, 2019). A disorder resulting from loss of function or tissue destruction of an organ or multiple organs, arising from humoral or cellular immune responses of the individual to their own tissue constituents. "The genes harboring these mutations, including DGKI, TNFRSF10A, GNGT1, CPAMD8, and BAFF, which are expressed in both eye and brain tissues and/or are related to autoimmune diseases, provide new avenues to evaluate the inherited causes of these devastating autoimmune conditions." (PMID 31161422, 2019).
gastrointestinal stromal tumor (1 paper, 2021). "GNGT1 can be utilized to differentiate gastrointestinal stromal tumor and leiomyosarcoma, two cancers that have very similar histopathology, but require very different treatments." (PMID 33505535, 2021).
glaucoma (1 paper, 2021). Increased pressure in the eyeball due to obstruction of the outflow of aqueous humor. "These 13 glaucoma-associated genes can be divided into three functional groups: phototransduction-related genes (GNGT1, OPN1SW, PDE6A, PDC, CRX, CNGB1, GUCY2F), glutamate receptor (GR) genes (GRIN2B, GRIK3, GRIK4), and 5-hydroxytryptamine receptor (HTR) genes (HTR1A, HTR1E, HTR7)." (PMID 33874942, 2021).
lymph node metastasis (1 paper, 2025). "Additionally, the expression level of GNGT1 was significantly associated with lymph node metastasis, with significant upregulation of GNGT1 in the normal group versus the N0, N1, N2 and N3 groups." (PMID 40594780, 2025).
mastitis (1 paper, 2020). Inflammation of breast tissue during lactation or postpartum due to an obstructed duct or infection. "GNG11 and GNGT1 code for G proteins, which function as key attributes of innate immune responses, and these are involved in functions relating to mastitis resistance." (PMID 32580275, 2020).
osteosarcoma (1 paper, 2024). A usually aggressive malignant bone-forming mesenchymal neoplasm, predominantly affecting adolescents and young adults. "Six of these genes are increased (MYOM2, VEGFA, MUC1, IHH, GLI1 and GRIA1) and seven are decreased (VCAM1, EGFR, GPC3, IGF2, GNG12, GNGT1 and C3) in localized patients with poor prognosis that either relapse or die due to osteosarcoma." (PMID 38538763, 2024).
systemic lupus erythematosus (1 paper, 2025). An autoimmune multi-organ disease typically associated with vasculopathy and autoantibody production. "The analysis revealed that in GC patients with high GNGT1 expression, the top five enriched pathways were involved in cytokine–cytokine receptor interactions, DNA replication, the cell cycle, ECM–receptor interactions, and systemic lupus erythematosus." (PMID 40594780, 2025).
cancer (8 papers, 2019 to 2025). A tumor composed of atypical neoplastic, often pleomorphic cells that invade other tissues. "Given the importance of gene mutations in tumour growth, we used the TCGA database and cBioPortal software to conduct a thorough investigation of GNGT1 mutations across cancers." (PMID 40594780, 2025). "The transducin γ-subunit gene (GNGT1) has been localized to human chromosome 7 and is associated with various forms of cancer." (PMID 33505535, 2021). "In line with other GNG family member genes in cancer, GNGT1 mRNA was highly expressed in GC tissues." (PMID 40594780, 2025). "GNGT1 was substantially found to be overexpressed in 14 cancer types relative to normal tissues, according to a pan-cancer characterization of its expression in the TCGA database." (PMID 40594780, 2025). "Nevertheless, we also recurrently identified some other candidate TAAs across many cancer types, such as GNGT1 in 23 cancer types, USP41 in 17 cancer types, and DEFB126 in 16 cancer types." (PMID 39561714, 2024). "L1PA2-L1PB1 expression was significantly upregulated in multiple types of cancer and was found at higher levels than transcription of GNGT1, which was also cancer-specific." (PMID 37502711, 2023). "Of note, HERVH Xp22.32 activation is mutually exclusive with activation of the L1PA2-L1PB1 elements at the GNGT1 locus, which is also cancer-specific, indicating the existence of EAC subsets." (PMID 37502711, 2023). "However, rigorous bioinformatics investigations are needed to delve deeper into the role of GNGT1 in cancer progression to elucidate its particular significance in the development of GC." (PMID 40594780, 2025). "A growing number of studies have recently shown that GNGT1 is abnormally expressed in various malignancies and may contribute to the initiation and spread of numerous cancers." (PMID 40594780, 2025). "As for methylation, GNGT1, KCNS3, GCG and PPKACG tended to be hypomethylated in pan-cancer while ADCY8 tended to be hypermethylated." (PMID 39104385, 2024). "While, difference in the expression of GNGT1 and NRXN1 was not significant in NPC samples compared with non-carcinoma samples." (PMID 34544905, 2021).
tumor (7 papers, 2019 to 2025). "To confirm that GNGT1 is expressed in GC, we assessed RNA-sequencing data from 36 TCGA normal tissues and 412 GC tumour tissues." (PMID 40594780, 2025). "Nevertheless, the potential role of GNGT1 in GC and how it is related to the tumour immune environment, particularly in terms of immune function regulation, remain unexplored." (PMID 40594780, 2025). "Multiple databases were used to evaluate the significance of GNGT1 in the GC tumour microenvironment (TME), immune cell infiltration, immune checkpoint expression, immune cell genetic marker expression and immune function." (PMID 40594780, 2025). "Additionally, GNGT1 expression differed significantly between the grade 1 and grade 2 groups and the grade 1 and grade 3 groups, suggesting that the GNGT1 levels in grade 2 and 3 tumours were much greater than those in grade 1 tumours." (PMID 40594780, 2025). "In terms of tumour stage, GNGT1 mRNA expression was considerably greater in the stage II, III, and IV groups than in the normal group, and the stage IV group presented the highest GNGT1 expression." (PMID 40594780, 2025). "Among them, the expression of CNR2, GIP, GNGT1, NPY1R, SSTR5, and LEP in tumor tissue was significantly lower than in normal tissue, while the expression of GPSM2, and NMU was significantly highly expressed in tumor tissue." (PMID 33169793, 2020). "However, GNGT1 was downregulated in the tissues of both LGG and PRAD tumours, which might be related to these tumour types have distinct tumorigenic pathways." (PMID 40594780, 2025).
neurodegenerative disease (1 paper, 2024). A disorder of the central nervous system characterized by gradual and progressive loss of neural tissue and neurologic function. "It remains unknown whether GNGT1 is involved in the ferroptosis of neurodegenerative disease." (PMID 39739972, 2024).
GNGT1 also shares sentences with these, for which no sentence is quoted: cognitive deficits (1 paper); leiomyosarcoma (1); multiple sclerosis (1); neuropathy (1); non-small cell lung carcinoma (1); retinal degeneration (1); retinal diseases (1); retinitis pigmentosa (1); urothelial carcinoma (1).